RARG (retinoic acid receptor gamma)
Description:
Receptor for retinoic acid. Retinoic acid receptors bind as heterodimers to their target response elements in response to their ligands, all-trans or 9-cis retinoic acid, and regulate gene expression in various biological processes. The RAR/RXR heterodimers bind to the retinoic acid response elements (RARE) composed of tandem 5'-AGGTCA-3' sites known as DR1-DR5. In the absence of ligand, acts mainly as an activator of gene expression due to weak binding to corepressors. Required for limb bud development. In concert with RARA or RARB, required for skeletal growth, matrix homeostasis and growth plate function (By similarity).
Synonyms: RAR-gamma; NR1B3; RARC; RARgamma
Tractability: Small molecule: an approved drug acts on it; a structure with a bound ligand is known; a high-quality ligand is known; it has a binding pocket of medium quality; it belongs to a druggable protein family. PROTAC: it is named in the literature on targeted protein degradation; UniProt records ubiquitination sites on it; ubiquitination databases record sites on it; a small molecule that binds it is known.
Target class: Nuclear hormone receptor subfamily 1 group B; Nuclear hormone receptor subfamily 1 group B member 3; Nuclear hormone receptor subfamily 1; Nuclear receptor; Transcription factor
Chemical probes: AHPN (high quality), CHEMBL330998, PD080973
Safety:
Unwanted effects reported when the protein is acted on. In parentheses: how it was acted on, where the effect was seen, and who reports it.
anthracycline-induced cardiotoxicity (source: ClinPGx)
Gene: Protein-coding gene on chromosome 12 (53,210,566 to 53,232,980, reverse strand). Ensembl gene ENSG00000172819.
Subcellular location: Nucleus; Cytoplasm
Subcellular location (Human Protein Atlas): Nucleoplasm
Pathways (Reactome):
Developmental Biology: Activation of anterior HOX genes in hindbrain development during early embryogenesis
Gene expression (Transcription): Nuclear Receptor transcription pathway
Signal Transduction: Signaling by Retinoic Acid
Gene Ontology:
Molecular function: protein binding; sequence-specific double-stranded DNA binding; DNA binding; DNA-binding transcription factor activity; DNA-binding transcription factor activity, RNA polymerase II-specific; nuclear receptor activity; nuclear retinoid X receptor binding; RNA polymerase II cis-regulatory region sequence-specific DNA binding; chromatin binding; sequence-specific DNA binding; zinc ion binding
Biological process: response to retinoic acid; retinoic acid receptor signaling pathway; canonical Wnt signaling pathway; cell differentiation; embryonic eye morphogenesis; embryonic hindlimb morphogenesis; negative regulation of cell population proliferation; negative regulation of transcription by RNA polymerase II; positive regulation of apoptotic process; positive regulation of programmed cell death; positive regulation of transcription by RNA polymerase II; regulation of cell size; bone development; chondrocyte development; growth plate cartilage chondrocyte growth; limb development; regulation of DNA-templated transcription
Cellular component: chromatin; cytoplasm; nucleoplasm; nucleus; membrane; RNA polymerase II transcription regulator complex; transcription regulator complex
Genetic constraint (gnomAD): Loss-of-function variants: 17 observed, 42.23 expected, observed/expected ratio (o/e) 0.4, 90% interval 0.28 to 0.6. The upper end of that interval is the gene's LOEUF score, 0.6, which puts it in group 2 of 6, group 1 being the genes least tolerant of losing a copy. Missense variants: 346 observed, 597.18 expected, observed/expected ratio (o/e) 0.58, 90% interval 0.53 to 0.63. Synonymous variants: 238 observed, 234.56 expected, observed/expected ratio (o/e) 1.01, 90% interval 0.91 to 1.13.
Homologues: Orthologues: macaque RARG (100% identical), chimpanzee RARG (99% identical), guinea pig RARG (98% identical), mouse Rarg (98% identical), pig RARG (98% identical), dog RARG (87% identical), rat Rarg (87% identical), tropical clawed frog rarg (84% identical), zebrafish rarga (79% identical), zebrafish rargb (75% identical), Caenorhabditis elegans sex-1 (28% identical), Caenorhabditis elegans nhr-19 (22% identical), and 180 more. Paralogues in human: RARB (72% identical), RARA (70% identical), RORA (31% identical), NR1D2 (29% identical), RORC (29% identical), RORB (29% identical), PPARA (28% identical), NR1D1 (28% identical), THRB (28% identical), NR1H2 (26% identical), PPARD (25% identical), THRA (25% identical), and 6 more.
Diseases named in the same sentence as RARG in open-access papers:
RARG is named in the same sentence as 97 diseases in open-access papers, as found by Europe PMC text mining. Sharing a sentence is not in itself a finding about the gene and the disease. The quoted sentences say what the papers report.
breast carcinoma (16 papers, 2009 to 2025). "ETS2 promotes telomerase expression, RARG has been linked with tamoxifen resistance in breast cancer patients, and VEZF1 is a regulator of angiogenesis." (PMID 37367050, 2023). "TFF3 and RARG were strongly expressed in breast cancer tissues, supporting their involvement in TNBC pathogenesis." (PMID 40969325, 2025). "The findings from in vitro studies of PCa and breast cancer cells and in vivo studies of lung cancer support the further development of the RARγ antagonist AGN205728 and/or the pan-RAR antagonist AGN194310 for use to treat these cancers." (PMID 35563205, 2022). "Based on this threshold, RARA was expressed in all breast cancer cases, whereas RARG was detectable in less than 2% of cases in the METABRIC cohort." (PMID 33148314, 2020). "Alternatively, the opposite effects of RA on breast cancer cell growth were induced by either RARA or RAR gamma (RARG)." (PMID 32823855, 2020). "The expression of both MR and RARB was higher in normal breast tissues and decreased in breast cancers while the expression of RARG and RARA was high and largely invariant in both sample cohorts." (PMID 33148314, 2020). "In particular, alternatively spliced variants of PRMT2 were related to survival and the invasiveness of breast cancer cells, while high expression of RARG and HOXA9 has been observed in human hepatocellular carcinomas and acute leukemia." (PMID 24401680, 2014). "We previously showed that in transgenic mice bearing MMTV-Neu- and -Wnt1-driven tumors, and report here that in mice bearing MMTV-Myc-driven tumors and in human breast cancer cell lines, RARγ expression is counterproductive to the anti-cancer effects of ATRA." (PMID 22920668, 2012). "In contrast, the RARγ isotype had pro-tumorigenic activity in liver cancer models, and its activation stimulated breast cancer cell proliferation." (PMID 22920668, 2012). "We found that over-expressing c-Myc in normal mouse mammary epithelium and in a c-Myc-driven transgenic model of mammary cancer, disrupts the balance between RARγ and RARα/β in favor of RARγ." (PMID 22920668, 2012). "It has been reported that RARγ is expressed at similar low levels in normal mammary epithelial cells, immortal breast cells, and breast cancer." (PMID 19442290, 2009). "In addition to the role of RARγ in Myc-mouse mammary epithelial cells, we documented its pro-oncogenic role in human breast cancer cells lines." (PMID 22920668, 2012). "The RARγ agonist significantly induced the growth of MCF7 breast cancer cells." (PMID 22920668, 2012). "PUS1 plays a role in the interaction between steroid receptor RNA activator 1 (SRA1) with the retinoic acid receptor-gamma (RARG) and the estrogen receptor in melanoma and breast cancer cells, respectively." (PMID 33430133, 2021). "Using the METABRIC breast cancer microarray dataset, we first examined the expression levels and degree of variance of MR, RARA, RARB and RARG in the cohort." (PMID 33148314, 2020). "As RARα mediates the anti-proliferative action of ATRA in breast cancer cells, we exposed SK-BR-3 cells to ATRA, AM580 (RARα-agonist), UVI2003 (RARβ-agonist) and BMS961 (RARγ-agonist)." (PMID 32384653, 2020). "Unexpectedly, we found that 3‐Cl‐AHPC, a synthetic ligand of RARγ and a potent cancer inhibitor, strongly induced the formation of matriptase/HAI‐1 complex in breast cancer cell MCF‐7, skin cancer cell A431 and colon cancer cell SW620." (PMID 30370662, 2019). "To establish whether ATRA modulates the expression of RARα, RARβ and RARγ, we exposed six TNBC and six retinoid-sensitive Luminal breast cancer cell lines to ATRA (1 μM) for 24 h." (PMID 33081033, 2020). "Knockdown of RARγ expression in immortalized epithelial MCF-10A (ER-, non-tumorigenic), MCF-7 (ER+, tumorigenic) and MDA-MB-231 (ER-, PR- and HER2-,tumorigenic) breast cancer cell lines led to their reduced proliferation." (PMID 22920668, 2012).
hepatocellular carcinoma (16 papers, 2012 to 2025). A malignant tumor that arises from hepatocytes. "Most human hepatocellular carcinoma tissue samples and hepatocellular carcinoma cell lines had significantly elevated levels of RARγ, and RARγ was seen to be mainly in the cytoplasm." (PMID 40362593, 2025). "Accordingly, RARγ has been reported to be seen predominantly in the nucleus, for example, in prostate cancer, or in the cytoplasm, for example, in hepatocellular cancer." (PMID 40362593, 2025). "Secondly, RARγ is an oncogene for several cancers, as evidenced by overexpression in human colorectal cancer, cholangiocarcinoma, hepatocellular cancer, ovarian cancer, pancreatic ductal adenocarcinoma, and renal cell cancer." (PMID 38928275, 2024). "Overexpression of RARγ was observed in the cytoplasm of hepatocellular cancer tissues and the HepG2 cell line cells, and RARγ transfection promoted HepG2 colony formation in vitro and the growth of HepG2 xenografts in mice." (PMID 38928275, 2024). "A role in modulating intracellular signaling for cell survival and growth was proposed for RARγ overexpression in the cytoplasm of hepatocellular cancer cells." (PMID 37569466, 2023). "RARγ is an oncogenic protein for hepatocellular carcinoma because it is significantly elevated in most human tumour tissue samples and the human hepatocellular carcinoma HepG2, QCy-7703, and QSG-7701 cell line cells." (PMID 36768694, 2023). "Overexpression of RARγ within hepatocellular cancer cell line cells promoted colony formation and the growth of xenografts in nude mice." (PMID 37569466, 2023). "Acacetin was used to target RARγ within hepatocellular carcinoma, and there was strong inhibition of the growth of hepatocellular carcinoma cell lines and SW480 and SW620 colorectal cancer cell line cells." (PMID 36768694, 2023). "Over-expression of RARγ promoted colony formation by hepatocellular carcinoma cells in vitro and the growth of xenografts, and the use of siRNA to down-regulate expression impaired ATRA induction of the disease marker alpha-fetoprotein." (PMID 36768694, 2023). "Treatment of hepatocellular carcinoma cells with the flavenoid acacetin, which interferes with the action of RARγ, decreased cell growth and induced apoptosis." (PMID 36768694, 2023). "RARγ is present in both the nucleus and cytoplasm of cells, and the natural flavonoid acacetin (5,7-dihydroxy-4-methoxyflavone) from Flos Chrysanthemi indici targeted the cytoplasmic action of RARγ within hepatocellular carcinoma cells." (PMID 36768694, 2023). "RARγ is overexpressed in human colorectal cancer, cholangiocarcinoma, hepatocellular cancer, ovarian cancer, pancreatic ductal adenocarcinoma, and renal cell cancer." (PMID 37569466, 2023). "RARγ overexpression within colorectal carcinoma, cholangiocarcinoma, and clear cell renal and hepatocellular carcinomas were measured for the cancer cell populations as a whole, rather than just for the CSC component." (PMID 36204679, 2022). "Overexpression of RARγ promotes the growth of hepatocellular carcinoma xenografts in mice and occurs in around 50% of cases of clear cell renal carcinoma." (PMID 36204679, 2022). "Second, RARγ is a putative oncogene for a number of human cancers, including cases of acute myeloid leukemia, cholangiocarcinoma, and colorectal, renal and hepatocellular carcinomas." (PMID 35563205, 2022). "It is overexpressed in, and is an oncogene for, many cancers including colorectal, renal and hepatocellular carcinoma, cholangiocarcinomas and some cases of acute myeloid leukemia that harbor RARγ fusion proteins." (PMID 33807298, 2021). "Levels of RARγ were significantly elevated in tumor tissues from a majority of human hepatocellular carcinoma and in hepatocarcinoma cell lines." (PMID 31590252, 2019).
hepatocellular carcinoma (continued). "We recently demonstrated that retinoic acid receptor-γ (RARγ) is overexpressed and acts as a tumor promoter in hepatocellular carcinoma (HCC)." (PMID 28336971, 2017). "Our results are in agreement with the proliferative role of RARγ in hematopoiesis and hepatocellular carcinoma." (PMID 22920668, 2012). "RARγ was overexpressed in the cytoplasm of cancer cells for reasons that are unknown, e.g., hepatocellular cancer, or within the nucleus, e.g., pancreatic cancer." (PMID 37569466, 2023). "Studies have found that RARG plays a vital role in the occurrence and development of many tumors, such as hepatocellular carcinoma, esophageal carcinoma and prostate cancer, and its expression level is closely related to the proliferation and migration ability of tumor cells." (PMID 36523991, 2022). "On one hand, RARG is significantly overexpressed in hepatocellular carcinoma, esophageal carcinoma, cholangiocarcinoma, colon cancer and other human cancers and plays an important role in promoting tumor progression through the PI3K/Akt, NF-κB, Wnt/β-catenin and other signaling pathways." (PMID 36523991, 2022). "RARγ has been previously reported as an oncogene in several cancers, including cholangiocarcinoma, hepatocellular carcinoma and colorectal cancer; however, in those cancers, the nuclear receptor RARγ was overexpressed in the cytoplasm rather than in the nucleus for unknown reasons." (PMID 37198667, 2023). "The majority of primary tissue samples from patients with hepatocellular carcinoma (HCC) overexpress RARγ, as do HCC cell lines." (PMID 35563205, 2022). "Our previous study identified that RARγ functions as a tumor promoter to drive hepatocellular carcinoma (HCC) growth." (PMID 27756432, 2016). "RARγ is an oncogene within some cases of AML, cholangiocarcinoma, colorectal cancer, clear cell renal cell carcinoma, hepatocellular carcinoma, pancreatic ductal adenocarcinoma, prostate cancer, and ovarian cancer." (PMID 36768694, 2023). "RARγ was present in the cytoplasm of hepatocellular cancer cells, and acacetin induction of apoptosis was reported to be due to antagonism of a non-genomic action of RARγ whereby cells were switched from pro-survival to pro-apoptosis." (PMID 40362593, 2025). "RARγ is frequently overexpressed in human CRC, cholangiocarcinoma (CCA) and hepatocellular carcinoma (HCC tissues)." (PMID 33807298, 2021).
prostate carcinoma (15 papers, 2004 to 2025). A carcinoma that arises from epithelial cells of the prostate gland. "Histological studies have associated high level RARγ expression with high-grade disease, metastasis, and a poor prognosis for cholangiocarcinoma and ovarian, pancreatic, and prostate cancer." (PMID 40362593, 2025). "Expression levels of retinoic acid receptor gamma (NR1B3/RARG, encodes RARγ) are commonly reduced in prostate cancer (PCa)." (PMID 30120411, 2019). "RARγ and RARα were increased significantly in high-grade prostate cancer, and a moderate to strong intensity of RARγ was seen in the nuclei of high-grade cells." (PMID 40362593, 2025). "Specifically, RARγ has been shown to be deregulated in prostate cancer and to influence the androgen receptor cistrome in malignant cell lines." (PMID 39633177, 2025). "Even so, there is support for the view that antagonism of RARγ is sufficient to kill CSCs (see table below for prostate cancer)." (PMID 40362593, 2025). "Overexpression and agonism of RARγ enhanced cell proliferation for head and neck, hepatocellular, and prostate cancer." (PMID 40362593, 2025). "Treatment of human prostate cancer cell lines with the RARγ agonist AGN205327 stimulated cell proliferation." (PMID 40362593, 2025). "RARγ-driven gene expression is favoured within prostate cancer cells due to their low intracellular level of ATRA because there is differential RARγ usage in prostate cancer tumours as revealed by the target genes are over-expressed." (PMID 36768694, 2023). "Most primary prostate cancer cells and the prostate cancer cell lines DU-145 and PC-3 express RARα and RARγ; the LNCaP cell line additionally expresses RARβ." (PMID 36768694, 2023). "RARγ activation is important to prostate cancer cell proliferation because the use of a RARγ agonist or a low level of ATRA (0.1 to 1 nM) to activate just RARγ stimulated the growth of and colony formation by prostate cancer cell line cells." (PMID 36768694, 2023). "Similar to PDAC cells, prostate cancer cells also express both RARα and RARγ, but the proliferation of tumor cells has been reported to depend only on RARγ." (PMID 37198667, 2023). "Treatment of the prostate cancer cell lines with the RARγ antagonist AGN205728 and the pan-RAR antagonist AGN194310 led to growth arrest in the G1 phase of cell cycle followed by necroptosis." (PMID 37569466, 2023). "The low intracellular level of ATRA in prostate cancer tumours is important because the RAR isoforms have a differential sensitivity towards ATRA transactivation: RARγ is activated at a much lower concentration of ATRA than RARα." (PMID 36768694, 2023). "The RARγ antagonist AGN205728 was more effective against prostate cancer cells than normal prostate epithelium and normal prostate RWPE-1 cells and did not affect cultures of human hematopoietic stem cells." (PMID 37569466, 2023). "Patients’ prostate cancer cells and human prostate cancer lines were more sensitive to the antagonism of RARγ and all RARs than normal human prostate epithelium and the human non-tumorigenic prostate line RWPE-1." (PMID 36768694, 2023). "Down-regulation of RARγ, a member of the nuclear receptor superfamily, has been shown to significantly affect the viability of prostate cancer cells and gene signature of these cells." (PMID 34831421, 2021). "Taken together, RARβ and RARγ seem to play an antioncogenic role in prostate cancer through an inhibitory effect on AR signaling by competitive binding to AR-binding sites." (PMID 31212954, 2019). "Data from Memorial Sloan Kettering Cancer Center and TCGA Prostate Adenocarcinoma showed that RARγ was significantly and uniquely downregulated in prostate cancer compared with other cancers." (PMID 31212954, 2019).